EGFR (epidermal growth factor receptor)
Diseases named in the same sentence as EGFR in open-access papers (continued):
Sharing a sentence is not in itself a finding about the gene and the disease.
tumor (continued). "Blockade of tumor growth is associated with downregulation of EGFR, HER2, and HER3 and reduced Akt phosphorylation, as well as the induction of endoplasmic reticulum stress." (PMID 31839995, 2019). "In NSCLC, elevated EGFR activity is associated with induction of IL-6 transcription, which in turn drives autocrine IL-6 signaling and tumor proliferation." (PMID 31741710, 2019). "We have developed a CAR based on the tumor-specific mAb806, which is selectively activated by tumor-expressed EGFR, be it full-length or the truncated EGFRvIII variant." (PMID 31903167, 2019). "This study demonstrated the association between NSCLC tumor uptake of radiolabeled cetuximab and EGFR protein expression levels in a xenograft mouse model." (PMID 31651282, 2019). "Real-time PCR analysis showed that the right-sided tumor had an epidermal growth factor receptor (EGFR) mutation presenting as point mutation T790M in exon 20, while the left-sided tumor had a point mutation L858R in exon 21 of EGFR." (PMID 31426797, 2019). "Approximately 10–15% of Caucasian NSCLC patients carry an activating EGFR mutation leading to a constitutive activation of the tyrosine kinase domain and downstream pathways involved in the tumor growth." (PMID 31557965, 2019). "Tumor tissue analysis is the gold standard to analyze EGFR mutations in NSCLC, and blood cannot be used as a surrogate source of analysis, as its sensitivity is not enough and depends on the platform used and the mutations analyzed." (PMID 30809319, 2019). "The EGFR mutation rate in tumor tissues was 32.26% (10/31), including 7 cases of deletion mutation in exon 19 (exon 19 Del) and 3 cases of L858R substitute mutation in exon 21 (exon 21 L858R)." (PMID 31608233, 2019). "In the advanced NSCLC subgroup, 14 of the 17 patients (82%) had the same EGFR-activating mutation in both tumour tissue and paired plasma." (PMID 30953094, 2019). "Further studies using human tumours are required to evaluate the usefulness of this tracer as a diagnostic tool of EGFR mutations." (PMID 30612556, 2019). "In contrast to cancer/testis antigens, tumor-associated antigens (TAAs), such as gp100, tyrosinase or EGFR, are overexpressed on tumor cells and are shared in a bigger patient population." (PMID 31040852, 2019). "In most cases, the allelic frequency of the other mutations was different as compared with the EGFR variant, suggesting intra-tumour heterogeneity." (PMID 30857358, 2019). "We first performed analysis of serum-derived cfDNA by using the Therascreen Plasma RGQ kit, which detected the same EGFR activating mutation found in tumor tissue at baseline in 13 out of 29 patients, showing therefore a 44.8% sensitivity." (PMID 31557965, 2019). "The anti-EGFR therapy in metastatic patients is led by the presence of KRAS-mutations in tumor tissue." (PMID 31673240, 2019). "Tumor growth curves indicated that EGFR-deficient tumor cells showed notably diminished growth rate than EGFR complete SKOV3-Luc coinjected with CAFs." (PMID 30710055, 2019). "Ectopic expression of EGFR in tumor xenografts attenuated senescence and tumor reduction caused by Nultin-3a." (PMID 30910997, 2019). "In our study, tumor specimens were previously analyzed for the determination of EGFR and ALK mutational status, by Sanger sequencing and FISH, respectively, according to recommendations at that time." (PMID 31443496, 2019). "Essentially, anti-EGFR TKI sensitization of tumor cells caused decreased sensitivity to FasLigand but remarkably enhanced cytotoxic degranulation activity of co-incubated NK cells in the presence of cetuximab." (PMID 31546690, 2019). "Recently, a liquid biopsy based medical test that detects several clinically significant EGFR somatic tumor mutations in the plasma of non-small cell lung cancer (NSCLC) patients has been approved by the FDA." (PMID 31998653, 2019). "Initially, tissue samples, biopsied from either primary tumor or metastatic lesions, had been used for the EGFR mutation testing." (PMID 31652678, 2019).
tumor (continued). "We analyzed the EGFR mutation status using ctDNA or tissue at the time of tumor progression to explore the mechanism of CHM in delaying the acquired resistance of TKI." (PMID 31333456, 2019). "It associates with EGFR to regulate cancer cell proliferation and activates several pathways important for tumor growth." (PMID 30837866, 2019). "AXL (AXL receptor tyrosine kinase) is associated with EMT in several tumours and its upregulation in the Hedgehog pathway has been recognized as a mechanism of resistance to targeted drugs in EGFR-mutated NSCLC." (PMID 31795465, 2019). "NGS analysis also revealed the presence of a p.T790M mutation of the EGFR in 9/133 tumour samples (6.8%)." (PMID 30857358, 2019). "For monitoring the EGFR mutation status after treatment, especially the occurrence of the secondary T790M mutation, the tumor tissue samples from rebiopsy procedures are needed." (PMID 30661185, 2019). "Although their clinical significance remains to be better determined, these findings do confirm that a substantial subgroup of patients with EGFRM+ NSCLC harbor some tumor cells with T790M co-mutation already before EGFR-TKI treatment." (PMID 31266248, 2019). "To assess the combined survival effect of the tumor tissue mRNA expression of 27 cytokines and variables, such as the clinicopathological parameters and the EGFR/KRAS mutation state, we applied multivariate survival analysis." (PMID 31004093, 2019). "In total, 31 of the 66 patients (47%) had EGFR-activating mutations in their tumour tissue and the remaining 35 patients had EGFR wild-type tumours." (PMID 30953094, 2019). "The principle of first blocking EGFR is based on eliminating the vasculature that promotes tumor growth after that the tumor cells become more susceptible to being eliminated by antiangiogenic therapy." (PMID 31303863, 2019). "When the EGFR mutation is found in tumor cells of a lung cancer, gefitinib, erlotinib, and afatinib, drugs that target this mutation, are used as successful treatments." (PMID 30542800, 2019). "Potentially actionable mutations detected from initial IDHWT tumours included EGFR, PTEN, BRCA1, BRCA2, ATM, and ATR." (PMID 32082376, 2019). "The polypyrimidine tract-binding protein PTBP1 was found to be highly expressed in many GBM specimens, causing aberrant splicing of annexin A7, a tumor suppressor, in turn resulting in enhanced EGFR signaling." (PMID 30644073, 2019). "In this study, EGFR mutation status was detected in tumor tissues as well as cell blocks and exosomes in MPEs, and the diagnostic value of exosome as a new DNA source for EGFR mutation detection was explored." (PMID 31608233, 2019). "Erlotinib is a reversible small-molecule ATP analogue which has been found to be most effective in advanced NSCLC patients with a tumor containing exon 19 deletions or a L858R mutation in exon 21 of the gene encoding the EGFR kinase domain." (PMID 31083571, 2019). "In total, 14 of the 31 patients (45%) with EGFR-activating mutations in their tumour tissue also had mutations in their plasma cfDNA." (PMID 30953094, 2019). "The aim of this study was to evaluate a fluorescent-labelled erlotinib-based tracer for the molecular imaging of EGFR-mutated tumours in vitro and ex vivo using a mice xenograft model and FCFM imaging." (PMID 30612556, 2019). "To date, although plasma sample cannot replace the tumor tissue in EGFR mutation testing, it contains cfDNA derived from different tumor locations, and thus seem to be more effective than tissue in reflecting the gene alterations during targeted treatment." (PMID 30661185, 2019). "After the cancer had progressed and the EGFR T790M mutation was detected in plasma, the tumor was treated with osimertinib for 6 months, but it grew from 59.05 to 72 mm." (PMID 31380273, 2019). "Intrinsic resistance can be caused by mechanisms inherent in EGFR or by EGFR-independent processes, including genetic, phenotypic or functional tumor changes." (PMID 31266248, 2019).
tumor (continued). "Risk stratification by primary tumor site and assessment of tumor laterality in patient selection for EGFR antibody treatment are also considered." (PMID 30736475, 2019). "The observation is in contrast to most reports in tumour tissue that indicate that PD-L1 expression is lower in EGFR mutation positive cases that wild-type variants." (PMID 30889898, 2019). "The detection of EGFR mutations in plasma ctDNA is a promising, minimally invasive, and reliable alternative to tumor biopsy, and the presence of EGFR mutations in plasma ctDNA after first-line EGFR-TKI therapy is associated with poor prognosis." (PMID 31185703, 2019). "These mutations are most likely acquired by the tumor as a means of escape from the continuous pressure exerted by anti‐EGFR MoAbs." (PMID 31350822, 2019). "In conclusion, TTS1 is an effective regimen for NSCLC previously heavily treated, especially in tumor EGFR mutated patients." (PMID 31579626, 2019). "Data have shown that patients with NSCLC harboring EGFR-activated mutations exhibit a dramatic tumor regression from EGFR tyrosine kinase inhibitors (TKIs), such as gefitinib and erlotinib." (PMID 31073278, 2019). "In the treatment of metastatic liver cancer with the EGFR inhibitor cetuximab, the tumor drug resistance is also associated with activation of STAT3." (PMID 30674340, 2019). "In fact, the targeted therapy of patients with EGFR-mutated tumours is more effective than conventional therapy; and the efficacy of EGFR tyrosine kinase inhibitors (TKIs) is increasing over generations of drugs." (PMID 31795465, 2019). "New methods are urgently needed to intuitively visualize the spatial distribution of EGFR mutations across whole tumor tissues and facilitate more accurate EGFR mutations detection." (PMID 31555581, 2019). "In the same study, tumor regression was observed in a patient-derived xenograft NSCLC model harboring an EGFR exon 20 insertion mutation following once daily dosing of TAK-788." (PMID 30854234, 2019). "Based on the paired specimens from the same patient (EGFR-L858R mutation) who initially benefitted from gefitinib treatment and then acquired resistance, we investigated the change in tumours before and after acquired EGFR-TKI resistance." (PMID 31747941, 2019). "As erlotinib and gefitinib bind to the intracellular domain of mutated EGFR, radio-labelled erlotinib and gefitinib have been assessed to image EGFR mutated tumours." (PMID 30612556, 2019). "Prolongation of tumor doubling time was observed, and treatment was tolerable in patients with EGFR mutation positive NSCLC who had received multiple prior therapies." (PMID 30915273, 2019). "We evaluated EGFR mutations in cfDNA as a complementary tool in patients, who had already known EGFR mutations in tumor tissue and were treated with either EGFR-tyrosine kinase inhibitors (TKIs) or chemotherapy." (PMID 30809319, 2019). "Overexpression of CD133 is associated with tumour progression through epidermal growth factor receptor (EGFR)-dependent Akt activation." (PMID 30836718, 2019). "EGFR activity has been implicated in proliferation, migration and differentiation of normal cells but also, in the malignant transformation of some tumor cells." (PMID 31069012, 2019). "In the present study, we identified the expression patterns of EGFR and its downstream pathway in pituitary corticotroph adenomas and investigated its association with clinicopathological characteristics and tumor recurrence." (PMID 31798535, 2019). "Secondary EGFR on-target mutations, most frequently T790M mutation, account for about half of relapsed tumours with acquired resistance." (PMID 31741433, 2019). "At a cut-off value of 354 Arbitrary Units, MFI of our tracer had a sensitivity of 100% and a specificity of 96.3% for identifying mutated EGFR tumours." (PMID 30612556, 2019). "Using a cut-off value of 354 A.U, MFI had a sensitivity of 100% and a specificity of 96.3% for identifying mutated EGFR tumours." (PMID 30612556, 2019).
tumor (continued). "Plasma cfDNA-based EGFR mutations analysis by ddPCR is useful in guiding clinical decisions in patients with insufficient or unavailable tumor specimens." (PMID 31413754, 2019). "Imaging features that have been associated with the primary tumor in EGFR-mutant NSCLC include peripheral location, pleural tagging, air bronchograms, and ground-glass opacities." (PMID 31540242, 2019). "Accordingly, the RAS wt tumors deriving from the left colon would be more responder to CT in association with anti-EGFR drugs as compared to the right-sided neoplasms." (PMID 31500586, 2019). "EVs, found in the circulation of cancer patients refractory to therapy, can also transport nucleic acids molecules of wild-type EGFR and mutated EGFR that reflect the genetic signature of the original tumor." (PMID 31877735, 2019). "The major drawback with these inhibitors was development of tumor resistance mainly due to EGFR T790M resistance mutation after a period of time." (PMID 30997737, 2019). "In both tumor locations, anti-EGFR antibodies were associated with higher overall response rates as compared to those associated with anti-VEGF antibodies." (PMID 30800219, 2019). "Tumours harbouring mutated forms of these genes are resistant to anti-epidermal growth factor receptor (EGFR) therapy." (PMID 31164962, 2019). "Among the 120 single tumor cells amplified successfully, DNA sequencing showed that the overall rates of EGFR L858R mutation and wild type gene were 77.5% (93/120) and 22.5% (27/120), respectively." (PMID 31014278, 2019). "The clinical validity of ddPCR Lung cfDNA Assay was first evaluated in terms of the concordance of EGFR mutations detected between paired tumor tissue specimens and plasma samples obtained from 106 EGFR-TKIs treatment-naïve patients." (PMID 31413754, 2019). "As ki-67 LI in tumor tissues is a widely accepted proliferation marker and a hallmark of tumor in the clinic 42, we also investigated the association between EGFR in EVs and ki-67 LI." (PMID 31410219, 2019). "Approximately after one year of EGFR-directed TKI therapy, resistance develops comprising several distinct mechanisms including the most common EGFR T790M mutation in 50%-60% of tumor samples." (PMID 35582592, 2019). "The p.T790M mutation has been previously reported in approximately 2% of TKI-naive EGFR-mutant tumours when routine diagnostic methods are used for testing." (PMID 30857358, 2019). "EGFR expression has been associated with several downstream pathways leading to a high tumor proliferation rate, inhibition of apoptosis, enhanced tumor invasion, and metastasis." (PMID 30630536, 2019). "Although a rebiopsy has been required to assess the T790M mutation status of a tumor after the development of resistance to EGFR‐TKIs, this procedure is often problematic depending on the size and location of the tumor." (PMID 31419057, 2019). "Monoclonal antibodies (McAbs) which target tumors mainly include drugs that target tumor-driving genes, inhibit protein kinase complexes by targeting the fusion mutation of EGFR, ALK, etc., or drugs which target angiogenesis (e.g., axitinib or sorafenib)." (PMID 31014381, 2019). "Among patients with CRC, some of them have poor survival based on the expression of EGFR associated with tumor growth." (PMID 31426807, 2019). "In conclusion, the use of this tracer was associated with a high sensitivity to detect swiftly mutated EGFR tumour." (PMID 30612556, 2019). "Through an evolutionary analysis of the sequencing results, the EGFR p.L861Q mutation was determined to play a role in the progression from the primary tumor to a relapsing tumor in one patient." (PMID 31822636, 2019). "After confirming the validity of the single-cell analysis system, we examined the presence of intratumoral heterogeneity of the EGFR mutation in adenocarcinoma NSCLC tumor tissues." (PMID 31014278, 2019).
tumor (continued). "Conventionally, the anti-tumor effects induced by kinase inhibitors are associated with their ability to inhibit the kinase activity of EGFR." (PMID 31121829, 2019). "The EGFR gene mutation abundance of body fluid supernatant free DNA was higher than that of body fluid sedimentary tumor cells and plasma free DNA specimens (100% vs. 90% vs. 80%, respectively, all P < 0.05)." (PMID 31602787, 2019). "Altogether, our data demonstrate the in vivo anti-tumor activity of Atorvastatin as a single agent against the clinically relevant TKI-resistant EGFR T790M/L858R mutation." (PMID 31534543, 2019). "In conclusion, in vivo and in vitro studies demonstrated that PCC0208027 had strong anti-tumor activity on NSCLC tumors with drug-sensitive EGFR mutations, drug-resistant EGFR mutations, and HER2 amplification." (PMID 30952931, 2019). "In the present study, we found that apigenin alone mildly suppressed the growth and proliferation of tumor cells with activating EGFR mutations, while ABT-263 can significantly enhance the antitumor effects of apigenin on EGFRm tumor cells." (PMID 31367332, 2019). "Since the discovery of EGFR mutations that promote tumor proliferation/metastasis, the development of tyrosine kinase inhibitors (TKIs) as targeted therapeutics has radically changed NSCLC treatment." (PMID 31396478, 2019). "EGFR mutations are widely involved in tumor proliferation and survival, and are also identified as the therapeutic target of EGFR tyrosine kinase inhibitors (TKIs)." (PMID 31428570, 2019). "The concordance rate of EGFR mutation between cfDNA and tumor tissues depends heavily on detection methods, ranging from 31% to 100%." (PMID 31870098, 2019). "By drug screening, we found that ABT-263 can significantly enhance the antitumor efficacy of apigenin in tumor cells harbouring activating EGFR mutations." (PMID 31367332, 2019). "In LADC, the altered tumor microenvironment caused by hydrogen peroxide can potentially cause the dysregulation of EGFR, EpoR, and ITGB1 (CD29) signaling pathways." (PMID 31217907, 2019). "Secondary endpoints included assessment of progression free survival (PFS), overall survival, change in tumor growth rate, safety and toxicity, and the evaluation of specific EGFR mutations and MET amplification in pre-treatment tissue and plasma." (PMID 30915273, 2019). "Further analyses revealed that therapeutic benefit of combined gemcitabine/EGFR inhibition associated with KRAS wild‐type tumour status 179, 180 or development of skin rash in patients, which represents another measure of EGFR inhibitor activity." (PMID 31330086, 2019). "Only surgical patients developing metastasis at a later time or patients with recurrence of tumor disease are retrospectively analyzed for EGFR mutations." (PMID 31083571, 2019). "Despite patient selection for anti‐EGFR MoAbs based on RAS mutations in the tumor, only 40–45% of patients with wild‐type mCRC have clinical benefits resulting in partial response in 8–13% and stable disease in 32% of patients." (PMID 31350822, 2019). "In this work, we develop a multiscale model capable of describing the effects of mutational changes in the EGFR/ERK pathway on tumour initiation." (PMID 31016574, 2019). "In contrast, another report suggested that a subgroup of EGFR mutant tumours with concomitant driver mutations affected the activity of first-line EGFR TKIs." (PMID 31739412, 2019). "A common example of this approach is the measurement of EGFR gene mutations to direct certain tyrosine kinase inhibitor (TKI) therapeutics that show improved efficacy in mutated tumours." (PMID 31190176, 2019). "TEADs play important roles in tumor progression and drug resistance downstream of the hyperactivating mutations on EGFR, KRAS, or BRAF." (PMID 31212916, 2019).